PTH (parathyroid hormone)
Diseases named in the same sentence as PTH in open-access papers (continued):
Sharing a sentence is not in itself a finding about the gene and the disease.
osteoporosis (continued). "Daily injection of PTH is the only anabolic treatment for patients with osteoporosis at high risk of fracture." (PMID 34978631, 2022). "An increased risk for osteoporosis exists among postmenopausal women, attributable to the presence of decreased estrogen levels, which can lead to increased sensitivity to PTH and subsequent bone resorption." (PMID 35573562, 2022). "Patients with PA had a higher plasmatic PTH, lower 25(OH)vitamin D serum levels, a higher prevalence of vitamin D deficiency, and a higher prevalence of osteopenia/osteoporosis compared to EH and controls." (PMID 36313775, 2022). "Decreased levels of estrogen and greater sensitivity to PTH put postmenopausal women at a higher risk of developing osteoporosis and encountering fracture injuries." (PMID 35573562, 2022). "This opens prospects for overcoming the problems of using PTH for bone regeneration and the treatment of osteoporosis, associated with the multiplicity of effects of this hormone on resident bone tissue stem cells." (PMID 36359914, 2022). "Mg deficiency contributes to osteoporosis directly by acting on crystal formation and on bone cells and indirectly by impacting the secretion and the activity of the parathyroid hormone and by promoting low-grade inflammation." (PMID 36141646, 2022). "Other risk factors of osteoporosis included gene, cigarette smoking, alcohol consumption, abnormally high plasma serum parathyroid hormone (PTH) levels, physical inactivity, and chronic use of some medications, for example, corticosteroids." (PMID 33849514, 2021). "The fact that the impaired response to PTH was most evident in female mice, is of particular interest since women are at greatest risk for osteoporosis and an anabolic PTH treatment regimen is an approved treatment for that disease." (PMID 33607650, 2021). "In the population under examination, we found hypovitaminosis D in 82.8% of patients and high levels of PTH in 20.7%, conditions known to be associated with an increased risk of osteoporosis.." (PMID 34876084, 2021). "Less severe vitamin D inadequacy leads to elevation of PTH (secondary hyperparathyroidism), leading to increased bone demineralization, bone loss, and finally osteoporosis and fracture." (PMID 33510909, 2021). "Absorption of calcium in the intestines was reduced because of low levels of vitamin D, leading to an increase of parathyroid hormone levels and bone turnover, subsequently, osteopenia and osteoporosis." (PMID 35223754, 2021). "The mechanisms whereby SHPT increases the risk of fracture mainly involve osteitis fibrosa and osteoporosis following persistently elevated parathyroid hormone (PTH) levels." (PMID 34132848, 2021). "We intend to expand our knowledge of the genetic polymorphisms in PTH and PTHRs among postmenopausal Arab women with osteoporosis from this preliminary evidence." (PMID 34977236, 2021). "PTH is recommended when patients are at a high risk of fracture or respond unsatisfactorily to or cannot tolerate other osteoporosis therapies such as bisphosphonates." (PMID 33584284, 2020). "We conclude that orchidectomy in male rats caused osteoporosis which was associated with significant reduction in serum levels of testosterone, PTH, OPG, OC and ALP and significant elevation in serum levels of RANK, DPD and NTx1." (PMID 33238425, 2020). "25(OH)D deficiency can lead to an increase in serum PTH, which can cause bone resorption, osteoporosis and fractures." (PMID 32415728, 2020). "Despite high PTH levels seen in primary hyperparathyroidism typically being associated with low bone mass and osteoporosis, patients with FHH manifest slightly reduced, normal, or even increased bone mass." (PMID 32213715, 2020). "A mildly severe 25(OH)D deficiency can lead to an increase in serum PTH, which can cause bone resorption, osteoporosis and fractures." (PMID 31988650, 2020).
osteoporosis (continued). "Hyperparathyroidism increases PTH levels and promotes bone absorption, which increases the risk of osteoporosis, indicating that the renin-angiotensin-aldosterone system (RAAS) is associated with osteoporosis." (PMID 32973674, 2020). "Some PTH formulations have been shown to reduce the risk of vertebral fractures, and are used in treating osteoporosis in postmenopausal women." (PMID 31106631, 2019). "Studies have shown a correlation between magnesium deficiency and osteoporosis, attributable to changes in parathyroid hormone (PTH), Vitamin D levels and increased pro-inflammatory cytokine secretion such as substance P, TNF-α, IL-1β, and RANKL." (PMID 32802092, 2019). "Excessive bone loss occurs in conditions with continuously elevated PTH (cPTH), such as primary hyperparathyroidism, where cPTH creates a catabolic effect that increases osteoclast number, eventuating in the onset of osteoporosis." (PMID 31713180, 2019). "Because PTH affects bone microarchitecture or turnover, most studies on PTH gene polymorphisms have focused on osteoporosis, bone mass, and bone size." (PMID 30760766, 2019). "Treatment of tHPT is mandatory since persistently elevated PTH concentrations after KTx increase the risk of renal allograft dysfunction and osteoporosis." (PMID 30729318, 2019). "PTH is also used to increase bone mass in men with primary or hypogonadal osteoporosis, who are at high risk of fracture." (PMID 31064048, 2019). "Patients with PHP and related disorders have several potential risk factors for osteoporosis (hypogonadism, chronic elevation of PTH and GH deficiency)." (PMID 29959430, 2018). "Phenylalanine and tyrosine levels have been associated with osteoporosis as through altering Ca homeostasis by activating the Ca receptor, and reducing the level of PTH, which initiates the process of demineralization and bone resorption." (PMID 29503615, 2018). "We found a high prevalence of untreated osteoporosis, vitamin D deficiency and parathyroid hormone elevations arising from vitamin D deficiency." (PMID 29439698, 2018). "As expected, PTH levels were higher in patients with osteopathy and associated with osteoporosis in the whole investigated population, but not in the sub-analysis conducted in male patients only." (PMID 30323223, 2018). "This phenomenon provides a new direction to gain insight into the mechanism underlying bone formation and lays the foundation for PTH research in vivo, which will be beneficial in the treatment of osteoporosis." (PMID 28437476, 2017). "Although there are no direct comparative studies that have been published, both teriparatide (PTH [1‐34]) and full‐length PTH (1‐84) appear to be effective for reducing fracture risk in patients with osteoporosis in a range of clinical studies and settings." (PMID 30283879, 2017). "In practical terms, this review can help clinicians who care for osteoporosis patients at high risk of fracture, understand the differences between different dosing intervals or administration routes of PTH and, thereby, make appropriate prescribing decisions." (PMID 30283879, 2017). "Owing to its high potential to increase BMD and reduce fracture risk, PTH is used for the treatment of osteoporosis patients that have a high risk of fracture." (PMID 28246925, 2017). "The anabolic effect of intermittently administered PTH has been illustrated in many studies leading to its’ FDA approval for high risk osteoporosis treatment." (PMID 27332712, 2016). "As recommended by Burgess, MHPT patients with elevated PTH greater than twice the upper limit of normal range should be considered as at risk for osteoporosis." (PMID 27846313, 2016). "In a number of studies, recombinant PTH has been demonstrated to have efficacy in treating osteoporosis and reducing subsequent fracture risk, but its benefit in fracture healing remains controversial." (PMID 25756046, 2015).
osteoporosis (continued). "The disease secondary tohyperparathyroidism is characterized by a negative calcium balance, associated or notwith vitamin D, which causes an abrupt increase in parathyroid hormone (PTH) levels,with consequent osteopenia or osteoporosis." (PMID 26537273, 2015). "Although most of these studies support a role for PTH in the treatment of osteoporosis and long bone fractures, only a few studies associated PTH treatment to calvarial healing." (PMID 26034928, 2015). "Vitamin D deficiency can lead to osteoporosis due to increased bone resorption caused by increased serum concentrations of parathyroid hormone (PTH)." (PMID 24934498, 2014). "Magnesium deficiency contributes to osteoporosis directly by acting on crystal formation and on bone cells and indirectly by impacting on the secretion and the activity of parathyroid hormone and by promoting low grade inflammation." (PMID 23912329, 2013). "The Food and Drug Administration (FDA) has also approved recombinant human parathyroid hormone (PTH) for the treatment of androgen-deficient osteoporosis." (PMID 22844328, 2012). "In particular, Mg2+ deficiency is well known as a potential risk factor of osteoporosis, as well as a cause of impaired parathyroid hormone (PTH) secretion, which in turn dysregulates Ca2+ homeostasis." (PMID 22837661, 2012). "Further adjustment for PTH levels and osteoporosis slightly attenuated the associations between 25OHD levels and physical performance measures (details not shown)." (PMID 22539952, 2012). "Teriparatide is a powerful analog of parathyroid hormone used to treat osteoporosis in postmenopausal women and men who are at high risk of fractures." (PMID 21042414, 2010). "Increased parathyroid hormone (PTH) secretion and bone turnover induced by poor vitamin D status and/or low calcium (Ca) intake is considered to increase the risk of osteoporosis in older people." (PMID 19394454, 2009). "Elevated homocysteine levels may be associated with higher PTH concentrations in individuals with osteoporosis." (PMID 42224245, 2026). "Therefore, this study does not relate the severity of primary hyperparathyroidism, in terms of calcium levels, duration of the condition, and PTH, to the risk of developing osteoporosis." (PMID 41156271, 2025). "Intestinal Ca malabsorption may also lead to hypogonadism-induced osteoporosis, causing a feedback rise in the PTH that promotes bone resorption and maintains the blood’s Ca levels balanced." (PMID 39780225, 2025). "Evaluating inflammatory markers might therefore be useful in identifying patients at heightened risk for osteoporosis and fragility fractures, beyond what can be predicted by PTH and calcium levels alone." (PMID 40529359, 2025). "Furthermore, to elucidate the relationship between FN-BMD, PMI, and traditional osteoporosis risk factors, including calcium (Ca), phosphate, and parathyroid hormone (PTH), we conducted a detailed investigation using multivariable linear regression analysis." (PMID 39748056, 2025). "Whereas prolonged elevation of circulating levels of PTH, as in hyperparathyroidism, increases turnover and leads to bone loss, intermittent daily PTH increases bone mass and is used as an anabolic agent in the treatment of osteoporosis." (PMID 40694420, 2025). "Interventional studies comparing the effect of vitamin D supplementation on insulin action and secretion, in ME immigrants and native Europeans, are needed as well as cohort studies addressing the incidence of osteoporosis and fracture risk in relation to the levels of 25(OH)D, PTH and Calcium." (PMID 39712337, 2025). "In a recent single-center, nonrandomized observational study, researchers evaluated the efficacy and safety of 1-year romosozumab administration (210 mg monthly), in 76 hemodialysis patients with osteoporosis, high risk of fracture, and PTH levels of 152.3 ± 172.0 pg/mL." (PMID 40177730, 2025).
osteoporosis (continued). "Renal wasting of phosphorus and calcium was linked to osteoporosis and increased intact PTH levels." (PMID 39176318, 2024). "In case of functional parathyroid tumors, additional blood assays offer the biological confirmation of primary hyperparathyroidism (high serum calcium and PTH), and further exploration of associated complications such as bone disease (including osteoporosis) or kidney anomalies is mandatory." (PMID 38791947, 2024). "In the case of vitamin D deficiency, PTH increases, which leads to osteoporosis." (PMID 39203838, 2024). "Similarly, a review emphasized that magnesium deficiency contributes to osteoporosis by directly affecting crystal formation and bone cells, and indirectly impacting the secretion and activity of parathyroid hormone and promoting low‐grade inflammation." (PMID 39055178, 2024). "Furthermore, low levels of vitamin D lead to high PTH levels causing high bone turnover, bone resorption, and osteoporosis." (PMID 37298368, 2023). "Furthermore, we demonstrate that therapeutic inhibition of miR‐19a/b enhances the increase in bone mass in response to PTH therapy and reduces bone loss in mouse models of osteoporosis induced by sex steroid deprivation." (PMID 36193848, 2022). "Similarly, an increase in the PTH level has been reported in postmenopausal women undergoing denosumab for osteoporosis and is associated with greater bone mineral density and greater inhibition of bone remodeling compared with zoledronic acid." (PMID 35740530, 2022). "This review will discuss the current literature regarding CVD risk and postmenopausal women’s osteoporosis prevention and treatment options, such as bisphosphonates, estrogen modulators, parathyroid hormone (PTH) analogs, and antiresorptive calcitonin analogs as an alternative therapy." (PMID 35573562, 2022). "The level of clinical difficulties because of the excess requirement of one or the other peptide, as well as the demonstration that an uncommon combination of PTH forms an abnormal bone mass, causes osteoporosis, making it evident how crucial PTH and PTHrP are." (PMID 36381723, 2022). "The role of magnesium as a modifiable risk factor for osteoporosis is now known, in consideration of the fact that low magnesium levels lead to reduced osteoblastic and osteoclastic activity, bone fragility, and strength or reduction of vitamin D and PTH." (PMID 34510395, 2022). "Age-associated reduction of Cx43 in osteoblasts has been linked to bone loss and osteoporosis, and it could diminish parathyroid hormone (PTH)-dependent bone formation." (PMID 34392490, 2021). "However, elevated PTH level can still be found in 30–60% at one year following transplantation and is associated with poor outcomes including osteoporosis, fracture, vascular calcification, and graft loss." (PMID 34071098, 2021). "Despite the associated risks, PTH is the most widely used drug for osteoporosis treatment." (PMID 33109775, 2020). "Adequate control of PTH in the post-transplant period is paramount given the increased risk of allograft dysfunction, allograft loss 13, 14, all-cause mortality 30, fractures, and osteoporosis." (PMID 30729318, 2019). "However, chronically elevated PTH levels cause bone resorption exceeding bone formation, ultimately resulting in osteoporosis and the risk of developing osteosarcoma." (PMID 31747888, 2019). "Chronically elevated PTH levels, as observed in primary and secondary hyperparathyroidism, cause a high bone-turnover state with bone resorption exceeding bone formation, ultimately resulting in osteoporosis." (PMID 30587780, 2018). "Thus, excess continuous PTH exposure, such as that seen in hyperparathyroidism, causes osteopenia or osteoporosis in humans." (PMID 30181648, 2018).
osteoporosis (continued). "In contrast to the loss of bone observed when PTH is continuously applied, intermittent application of exogenous PTH, for example the application of teriparatide in the treatment of osteoporosis, can have an anabolic effect on bone by increasing formation in both cancellous and cortical regions." (PMID 30364287, 2018). "If osteoporosis is diagnosed, management should take into account, whenever possible, treatment of the underlying secondary cause for bone loss (hypogonadism, postmenopausal status or related to sustained elevation of PTH levels and GH deficiency) (B++)." (PMID 29959430, 2018). "On the other hand, our data also showed that obesity had a negative correlation with vitamin D and a positive correlation with PTH which may indicate that obesity is a risk factor for osteoporosis which has been also shown by other investigators." (PMID 28124221, 2017). "Vitamin D deficiency and compensatory rise in PTH may influence the pathogenesis of increased osteoporosis risk in patients with TB." (PMID 29030560, 2017). "Indeed, parathyroid hormone, a bone formation agent in osteoporosis, was reported to protect alveolar bone loss in animal and human studies." (PMID 28937990, 2017). "For example, mice genetically deficient in PTHrP develop osteoporosis, whereas mice deficient in PTH exhibit increased bone mass that may be indirectly mediated by a local compensatory induction of PTHrP." (PMID 27395059, 2016). "Osteoporosis and secondary hyperparathyroidism are associated with a different diurnal rhythm (DR) of PTH and BTMs compared to healthy controls, suggesting that the DRs of PTH and bone remodeling are important for bone integrity (19, 21, –, 23)." (PMID 27294326, 2016). "To test whether rClec11a could reverse bone loss after the onset of osteoporosis we ovariectomized two month-old wild-type mice and waited for four weeks before administering PTH or rClec11a daily for another four weeks." (PMID 27976999, 2016). "Low serum Mg may cause insufficient PTH action and deteriorate osteoporosis in CKD patients, particularly those with diabetes." (PMID 26273297, 2015). "These CKD patients with high serum Mg levels, raised PTH levels, vitamin D deficiency, low Ca levels, and osteoporosis may be considered as having a high-turnover bone disease (bone resorption)." (PMID 26273297, 2015). "Additionally, cell-independent causes of osteoporosis, for example, decreased calcium absorption or increased parathyroid hormone excretion, remain possible explanations for the association between PPI use and fracture risk." (PMID 25873758, 2015). "Moreover, magnesium supplementation can correct osteoporosis combined with PTH and vitamin D deficiency." (PMID 25157571, 2014). "As the only approved anabolic agent, intermittent PTH therapy has been demonstrated to have beneficial effects on increasing bone mass and diminishing bone fragility associated with osteoporosis resulting from aging, sex hormone deficiency, and glucocorticoids use." (PMID 24800251, 2014). "Further studies are needed to investigate the impact of slightly elevated PTH and active bone remodelling on bone health, as impaired phosphocalcic profile and vitamin D metabolism has been shown to be implicated in bone diseases such as osteoporosis and other metabolic conditions." (PMID 41574189, 2025). "In recent decades, parathyroid hormone-related analogues (e.g., teriparatide and abaloparatide) and anti-sclerostin agents (e.g., romosozumab) have also been tested as anabolic therapies for osteoporosis, especially in individuals who are at high risk of fragility fractures." (PMID 41369394, 2025). "Current treatments for osteoporosis focus on prevention of bone loss or increases in bone mass using anti-resorptive, anabolic or combined anti-resorptive and anabolic drugs including bisphosphonates, parathyroid hormone (PTH)-related analogs, and sclerostin inhibitors." (PMID 40978132, 2025).